CREBBP (CREB binding lysine acetyltransferase )
Diseases named in the same sentence as CREBBP in open-access papers (continued):
Sharing a sentence is not in itself a finding about the gene and the disease.
infection (16 papers, 2014 to 2023). The state of being infected such as from the introduction of a foreign agent such as serum, vaccine, antigenic substance or organism. "Infection of K562 cells with lentiviruses expressing shRNAs against EP300 or CREBBP or both reduced the expression of the targeted proteins." (PMID 29884215, 2018). "Also, the STAT3, AKT1, MAPK9, MAPK14, and CREBBP were identified as host’s infection response regulators of bacterial Hcp in duck." (PMID 36262184, 2022). "Other studies have suggested that upregulation of miR-4474 and miR-4717 in CRC tissues in response to infection with F. nucleatum decreases expression of CREB-binding protein (CREBBP) and may promote progression of CRC." (PMID 34371938, 2021). "Interestingly, the expression levels of CREBBP mRNA in advanced-stage CRC with F. nucleatum positive infection was lower than the early-stage ones." (PMID 30951563, 2019). "Based in the activation of EZH2, HDAC7 and CREBBP is possible that the changes induced by the infection could be genomically imprinted." (PMID 30248353, 2018). "We next analyzed the protein-protein interaction network even further and demonstrated that the infection related proteins STAT3, AKT1, MAPK9, MAPK14, and CREBBP had the highest degree of connectivity among DAPs." (PMID 36262184, 2022). "During infection of influenza virus, a circRNA, AIVR, was upregulated to exerting its antiviral effect by absorbing miRNA and promoting the expression of CREBBP to facilitate IFN-β production." (PMID 35722302, 2022). "We found that the expression levels of CREBBP and IFN-β in the influenza virus-infected cells were also related to viral dose and infection time, which was consistent with the expression trend of AIVR." (PMID 34281396, 2021). "The Kinexus microarray did not contain antibodies against the activated form of several transcription factors (including SREBF1-2, CREBBP and SMAD3) that our TFactS analysis of transcriptomics data identified as modulated by infection." (PMID 28480889, 2017). "In addition, HepG2-NTCP cells were transfected with knockdown CREBBP in 24 wells, transfected for 48 hours, infected with HBV at a cell density close to 100%, and then harvested 5 days after infection to measure intracellular TGF-β2." (PMID 36727157, 2023). "However, the expression of CREBBP mRNA was significantly lower in F. nucleatum-positive CRC tissues than in the F. nucleatum positive controls (P<0.05) and was also lower in the early- and advanced-stage CRC with F. nucleatum positive infection (P<0.05)." (PMID 30951563, 2019). "Notably, E2 proteins interact with CREBBP/EP300 and this could enhance the formation and development of PEB-BLOCs in a natural infection." (PMID 24832099, 2014).
hematologic malignancies (9 papers, 2015 to 2025). "This allowed us to identify novel SNVs in genes previously reported as mutated in ALL or other hematological malignancies: CREBBP, CSF3R and DUX4." (PMID 41333018, 2025). "In this review, we summarize the role of CREBBP/EP300 in normal hematopoiesis and highlight the pathogenic mechanisms of CREBBP/EP300 in hematological malignancies." (PMID 36831561, 2023). "Genetic abnormalities of CREBBP/EP300 are frequent in hematological malignancies and include gene mutations, copy number variations, and structural variations." (PMID 36831561, 2023). "It is instructive to design personalized immunotherapy for hematological malignancies with CREBBP/EP300 driver mutations using next-generation sequencing technologies." (PMID 36831561, 2023). "CREBBP/EP300 gene mutations frequently occur in hematological malignancies through a variety of different mechanisms, resulting in poor patient prognosis, including worse overall survival (OS), progression-free survival (PFS), and event-free survival (EFS)." (PMID 36831561, 2023). "Aberrant CREBBP/EP300 expression is common in hematological malignancies and is associated with chemoresistance." (PMID 36831561, 2023). "The CREBBP target gene is known to harbor mutational hotspot regions predominantly accomplished with hematological diseases." (PMID 26057250, 2015). "To date, there is sufficient evidence that HDACis or other inhibitors of epigenetic modification molecules, alone or in combination, are effective against some hematologic malignancies with aberrant CREBBP/EP300 expression." (PMID 36831561, 2023). "We next tested whether co-administration of the orally-available, CREBBP bromodomain inhibitor Inobrodib, which is in early-phase trials in hematological malignancies, could sensitize 697WT cells to Venetoclax in-vivo." (PMID 40393984, 2025). "Transcriptional or epigenetic dysregulation of CREBBP/EP300 in hematological malignancies may lead to chemoresistance." (PMID 36831561, 2023). "However, a growing number of studies have shown that aberrant expression of CREBBP/EP300 is associated with tumorigenesis and the progression of hematological malignancies." (PMID 36831561, 2023). "Finally, we discuss some prospective therapeutic strategies for CREBBP/EP300 inhibitors in hematological malignancies." (PMID 36831561, 2023). "The reviewed information revealed that genetic aberrations of CREBBP/EP300 were observed in various types of solid tumors and hematologic malignancies and considered promising therapeutic targets." (PMID 40558049, 2025). "CREBBP/EP300 dysregulation and CREBBP/EP300-containing complexes are critical for the initiation, progression, and chemoresistance of hematological malignancies." (PMID 36831561, 2023). "Here, after providing a brief overview of the molecular characteristics and functions of CREBBP/EP300, we summarize the current knowledge about the implications of CREBBP/EP300 in normal hematopoiesis and hematological malignancies." (PMID 36831561, 2023). "As key acetyltransferase family members and transcriptional co-activators, CREBBP/EP300 regulate the acetylation levels of multiple substrates involved in the regulation of normal hematopoietic maintenance and the development of hematological malignancies." (PMID 36831561, 2023). "Here, this review discusses the critical role of CREBBP/EP300 in normal hematopoiesis and also provides a comprehensive overview of how they contribute to the genesis and progression of hematologic malignancies." (PMID 36831561, 2023). "In this review, we focus on summarizing several representative CREBBP/EP300 BRD inhibitors (CCS1477, CPI-637, and GNE272, etc.)and HAT inhibitors (A485, A-241, and C646, etc.)and their functions in hematological malignancies." (PMID 36831561, 2023). "Currently, CREBBP/EP300 are attractive targets for drug development and are increasingly used as favorable tools in preclinical studies of hematological malignancies." (PMID 36831561, 2023).
hematologic malignancies (continued). "Genetic aberrations of CREBBP/EP300 have been observed in various types of solid tumors and hematologic malignancies, making them serve as promising therapeutic targets." (PMID 36831561, 2023).
CNS tumors (5 papers, 2020 to 2024). "In two-sample MR study, CREB-binding protein (CREBBP) has a positive causality with benign CNS tumors (Inverse variance weighted beta = 0.2329, p = 0.01911)." (PMID 39043735, 2024). "BCOR fusions have also been identified in pediatric CNS tumors with two different gene fusion partners: EP300 and CREBBP." (PMID 39409964, 2024). "Two CNS tumors with fusions between CREBBP, or its paralog EP300, and BCORL1, and approximately twenty CNS tumors with CREBBP/EP300::BCOR fusions have been reported to date." (PMID 38216991, 2024). "After the first description of CNS tumor with BCOR ITD, other tumors with overlapping morphological and immunohistochemical features, but harboring fusions of BCOR with either EP300 or its paralog CREBBP, instead of BCOR ITD, have been reported in the CNS." (PMID 38216991, 2024). "In an additional 686 primary CNS tumor cases of adult and pediatric patients, assessed via FISH or RNA-seq analysis, we identified an additional case demonstrating a BCOR fusion to a paralog of CREBBP, namely EP300, similar to that seen in a recently reported series." (PMID 32493417, 2020).
hematologic cancer (4 papers, 2017 to 2025). "Our study shows that several hematologic cancer cell lines are sensitive to inactivation of CREBBP/EP300 bromodomains." (PMID 29884215, 2018). "In addition, other genes known to be affected by somatic mutations in hematologic cancers were also found from the WES data, such as JAK3, CREBBP, BCOR, and so on." (PMID 28410228, 2017).
autosomal dominant disease (1 paper, 2010). Autosomal dominant form of disease. "Peak heights were normalized against 3 reference probes (EXT1, CREBBP and EP300), selected from known autosomal dominant disease genes, which would not be deleted or duplicated without an obvious phenotype." (PMID 20957197, 2010).
neurodegenerative disease (1 paper, 2024). A disorder of the central nervous system characterized by gradual and progressive loss of neural tissue and neurologic function. "As shown by the program results DE miR-3687, miR-612, miR-4261, miR-504-3p, miR-126-5p,and miR-411-5p bind to the mRNA of the B3GNT2, CSMD2, ATN1, CREBBP, ATXN1, EMIN4, and EFNA5 genes, which are associated with neurodegenerative diseases." (PMID 39049823, 2024). "CREBBP gene may play a role in the pathogenesis of various neurodegenerative diseases, such as HD." (PMID 39049823, 2024).
neurodevelopmental disorder (1 paper, 2024). A behavioral and cognitive disorder with onset during the developmental period that involves impaired or aberrant development of intellectual, motor, or social functions. "Also, we have identified 15 de novo variants in genes that were previously implicated in ASD or related neurodevelopmental disorders (PHF21A, WASF1, TCF20, DEAF1, MED13, CREBBP, KDM6B,SMURF1, ADNP, CACNA1G, MYT1L, KIF13B, GRIA2, CHM, and KCNK9)." (PMID 38572415, 2024).
CREBBP also shares sentences with these, for which no sentence is quoted: esophageal squamous cell carcinoma (7 papers); Anxiety (4); viral infection (4); asthma (3); Burkitt lymphoma (3); depression (3); nasopharyngeal carcinoma (3); Rett syndrome (3); adenocarcinoma (2); carcinoma in situ (2); Cornelia de Lange syndrome (2); Down syndrome (2); endometrial cancer (2); ischemia (2); Kabuki syndrome (2); kidney clear cell carcinoma (2); liposarcoma (2); Menke-Hennekam syndrome 1 (2); neurological diseases (2); non-small cell lung carcinoma (2); renal fibrosis (2); thyroid cancer (2); -Taybi syndrome (1); acute monocytic leukemia (1); AIDS (1); Alagille syndrome (1); alcohol abuse (1); amyotrophic lateral sclerosis (1); anaplastic astrocytoma (1); Arrhythmogenic right ventricular dysplasia (1).
A further 110 diseases each share a sentence with CREBBP in 1 paper.